FGFR1 (fibroblast growth factor receptor 1)
Diseases named in the same sentence as FGFR1 in open-access papers (continued):
Sharing a sentence is not in itself a finding about the gene and the disease.
cholangiocarcinoma (31 papers, 2016 to 2025). A carcinoma that arises from the intrahepatic biliary tree (intrahepatic cholangiocarcinoma) or from the junction, or adjacent to the junction, of the right and left hepatic ducts (hilar cholangiocarcinoma). "In addition, we used an intrahepatic cholangiocarcinoma tissue microarray to investigate the correlations between FGFR1, VEGFR3 and HK2 expression and tumour-associated lymphangiogenesis and lymph node metastasis in patients with iCCA." (PMID 37433897, 2023). "Infigratinib is a selective FGFR1–3 inhibitor developed for FGFR2 fusion-positive cholangiocarcinoma." (PMID 41041285, 2025). "For instance, pemigatinib has received approval for the management of advanced cholangiocarcinoma because of its potent activity as a selective oral small-molecule inhibitor of FGFR1, FGFR2, and FGFR3." (PMID 40898491, 2025). "Pemigatinib, the first FGFR1/2/3 selective inhibitor received accelerated FDA approval for patients carrying FGFR2 fusion/rearrangement in cholangiocarcinoma." (PMID 36147913, 2022). "The FGFR1 gene has been suggested as a target of YAP in cholangiocarcinoma, as chromatin immunoprecipitation assays demonstrated the simultaneous nuclear presence of TBX5-YAP complexes on the promoter region of FGFR1." (PMID 31963871, 2020). "Approximately 11% of iCCAs were demonstrated to harbour gene fusions of FGFR1/2/3, which is rare in other cholangiocarcinomas." (PMID 30419854, 2018). "Pemigatinib, a small molecule inhibitor of FGFR1–3, has been approved in the US for treatment of unresectable cholangiocarcinoma with FGFR2 alterations, while erdafitinib, pan-FGFR inhibitor, is indicated for metastatic urothelial carcinoma with FGFR2 and FGFR3 alterations." (PMID 40393028, 2025). "Furthermore FGFR2 fusions/rearrangements events have demonstrated their clinical relevance in cholangiocarcinoma patients, which benefit from treatment with selective FGFR1-3 inhibitors." (PMID 35246724, 2023). "In fact, such a hypothesis is supported by the fact that LRIT3 is a regulator of FGFR1, one of the driver genes of cholangiocarcinoma." (PMID 35382169, 2022). "Thus, it is likely that YAP and TBX5 form a complex to regulate FGFR1 expression, similar to those described in cholangiocarcinoma." (PMID 31963871, 2020). "Infigratinib is a selective oral FGFR1–3 inhibitor designed for FGFR-altered cancers, particularly FGFR2 fusion-positive cholangiocarcinoma." (PMID 41041285, 2025). "In the majority of cases, genomic alterations mainly comprised SVs, except for FGFR1 alterations in salivary gland carcinoma and FGFR2 alterations in cholangiocarcinoma, in which REs were most common." (PMID 36462464, 2022). "This profile translates into potentactivity in xenograft tumor models with translocations in FGFR1 (8p11-translocatedmyeloid leukemia), FGFR2 (cholangiocarcinoma), and FGFR3 (urothelial carcinoma)." (PMID 32315352, 2020). "A further interesting aspect is that FGFR1, -2, and -4 are transcriptional targets of YAP, and a feed-forward loop has been described between YAP and FGFR signaling in cholangiocarcinoma and ovarian cancer." (PMID 30903103, 2019).
ovarian carcinoma (31 papers, 2011 to 2026). A malignant neoplasm originating from the surface ovarian epithelium. "Our results suggest that the significant diagnostic ability of FGFR1, but also note that more evidence is needed to improve disease prognosis and to design effective drugs to treat ovarian cancer." (PMID 33604191, 2021). "This isoform is highly expressed in ovarian-cancer associated vessels and has an increased potential to induce angiogenesis, which relies on FGFR1 signaling." (PMID 31455004, 2019). "Alterations in the fibroblast growth factor receptor 1 (FGFR1) have been linked to the development and progression of several types of cancer, including breast, lung, gastric, bladder, and ovarian cancers, and is associated with poor prognosis and resistance to chemotherapy." (PMID 37373291, 2023). "The meta analyses of ovarian cancer that we report here significantly extends our knowledge base to cognize that FGFR1 may be a good diagnostic biomarker in Asian populations." (PMID 33604191, 2021). "A present study has also investigated that FGFR1 rs2288696 may contribute to menarche timing in Ukrainian female, as well as early menarche onset is a known risk factor for breast and ovarian cancer in late adulthood." (PMID 30359238, 2018). "Our data suggested that tephrosin suppresses the FGFR1/FRS2 signaling pathway in paclitaxel-resistant ovarian cancer cells." (PMID 38137377, 2023). "This study demonstrates that tephrosin is a potent antitumor agent that can be used in the treatment of paclitaxel-resistant ovarian cancer via the inhibition of the FGFR1 signaling pathway." (PMID 38137377, 2023). "ERK und FAK are considered to be two of the main depending intracellular pathways stimulated by FGFR1 in lung and ovarian cancer." (PMID 37445817, 2023). "L1 cell adhesion molecule has been demonstrated to facilitate ovarian cancer cell spheroid formation, tumor initiation, and chemoresistance by triggering FGFR1 and its downstream SRC/STAT3 pathway." (PMID 37750089, 2023). "FGFR1 (Fibroblast Growth Factor Receptor 1) is overexpressed in the majority of human tumors, including ovarian cancer." (PMID 36185201, 2022). "Next, we investigated the expression patterns of FGFR1 in ovarian cancer samples from both datasets." (PMID 33604191, 2021). "In conclusion, this is a preliminary study designed to investigate the role played by FGFR1 in ovarian cancer." (PMID 33604191, 2021). "By using affinity purification/mass spectrometry (IP/MS) and reciprocal co-immunoprecipitation (co-IP) analyses, we found that GLT8D2 interacts with fibroblast growth factor receptor 1(FGFR1) in ovarian cancer cells." (PMID 34294681, 2021). "In ovarian cancer cells, α-2,6 sialylation of fibroblast growth factor receptor 1 (FGFR1) by ST6GAL1 activated the extracellular signaling-regulated protein kinase 1/2 (ERK1/2) and focal adhesion kinase (FAK) pathway, enhancing cell migration and drug chemoresistance." (PMID 33921986, 2021). "Interestingly, we found that GLT8D2 interacts with FGFR1 in ovarian cancer cells and activated FGFR signaling, subsequently activated the PI3K/AKT signaling pathway." (PMID 34294681, 2021). "Furthermore, the fact that in vivo suppression of tumorigenicity was lost with P95R indicated the biological importance of the AXL pathway in ovarian cancer despite an intact FGFR1/FGF1 axis." (PMID 31316070, 2019). "Furthermore, the FGFR1 rs2288696 is the protective SNP with the highest statistical significance in ovarian cancer." (PMID 30359238, 2018). "Therefore, it is our hypothesis that FGFR1 and TSC2 might be associated with platinum resistance in ovarian cancer." (PMID 27677586, 2016). "In ovarian cancers, OPCML drives inactivation and degradation of the RTKs HER2, HER4, FGFR1, FGFR3, EPHA2, and AXL, and the specificity of this network is underscored by identification of a group of RTKs that are unaffected by OPCML." (PMID 40699804, 2025).
ovarian carcinoma (continued). "Previous studies have tested FGFR1/2/3 inhibitors AZD454 and CPL304-110-01 in ovarian cancer cell lines, which demonstrated the therapeutic potential of these inhibitors." (PMID 39858026, 2025). "The CDK12 inhibitor reduced the expression of FGFR1 and other FGF receptors in ovarian cancer cells, leading to decreased cell proliferation and increased apoptosis." (PMID 37190191, 2023). "A recent study showed that ST6GAL1 overexpression induces α-2,6-sialylation of FGFR1 and that high levels of ST6GAL1 decrease the anticancer effect of the FGFR1 inhibitor PD173047 in ovarian cancer cells." (PMID 33921986, 2021). "Therefore, we considered FGFR1 might play an important role in diagnosing ovarian cancer." (PMID 33604191, 2021). "Both epidermal growth factor receptor (EGFR) and fibroblast growth factor receptor 1 (FGFR1) are overexpressed in the majority of human tumors, including ovarian cancer." (PMID 25919378, 2015). "Thus, we performed in vitro studies to determine the antitumor effects and mechanistic details of FGFRs in ovarian cancer using AZD4547, a small-molecule inhibitor of FGFR1–3." (PMID 34639155, 2021). "The expression of FGFR1 was significantly different in advanced ovarian cancer, but not in early ovarian cancer in GSE12470 (p = 0.0124)." (PMID 33604191, 2021). "Moreover, tumor cell lines with high FGFR1/3 expression were more sensitive to FGFR inhibitor PD173074, especially in breast, liver, lung and ovarian cancer." (PMID 32596330, 2020). "Moreover, using data from the GEO datasets, we also found that FGFR1 was downregulated in ovarian cancer samples relative to normal tissues." (PMID 33604191, 2021). "The expression levels of FGFR1 in ovarian cancer tissues were significantly lower than in non-cancer control tissues in both GSE105437 and GSE12470 with analyses performing Fold change cut-off adjusted to 2.0 and corrected p-values cut-off adjusted to 0.05(p < 0.0001 and p = 0.0032, respectively)." (PMID 33604191, 2021). "Collectively, these findings demonstrate that FGFR1 functions as a context-dependent tumor suppressor in OC by modulating SIRT3-mediated metabolic reprogramming and histone lactylation, suggesting that targeting the FGFR1-SIRT3 axis may represent a potential therapeutic strategy for ovarian cancer." (PMID 41946672, 2026). "However, the relationship between FGFR1 and ovarian cancer has not been well determined." (PMID 33604191, 2021). "The hub genes (e.g., FGFR1 and TSC2) which have not been reported in previous literature might be potential platinum resistance-related genes in ovarian cancer." (PMID 27677586, 2016).
breast tumors (29 papers, 2007 to 2025). "We show a positive association between FGFR1 and leptin protein copy number in primary breast tumors." (PMID 33019728, 2020). "We demonstrated that both LepR mRNA and FGFR1 mRNA were both positively associated with Jak2 mRNA in primary breast tumors." (PMID 33019728, 2020). "In a phase II trial (NCT01795768), the FGFR1/2/3 inhibitor AZD4547 demonstrated potential therapeutic effects in patients with FGFR1-amplified breast tumors." (PMID 40134916, 2025). "In conclusion, the present study showed increased FGFR1 expression in breast tumor tissue compared with paired tumor-adjacent breast tissue from the same patient." (PMID 37546410, 2023). "In the phase II trial (NCT01795768), AZD4547, an FGFR1/2/3 inhibitor exhibited a potential therapeutic effect on FGFR1-amplified breast tumor patients." (PMID 37415164, 2023). "In tissue samples obtained from consecutive surgeries of primary human breast tumors, FGFR1 was most abundantly expressed at the mRNA level, followed by FGFR4 and FGFR2." (PMID 33119860, 2021). "It has been reported that FGFR1 activation triggers the NF-kB signaling cascade in diverse cell contexts, including breast tumor cells." (PMID 33946884, 2021). "Common oncogenic drivers such as CCND1 and FGFR1 or FGFR2 were amplified in the primary breast tumours and can be considered early events in these patients’ tumours." (PMID 32792481, 2020). "We demonstrated that an increased FGFR1 copy number variation was significantly correlated with an increased leptin copy number in both ER+ breast tumors (7.8 × 10−5, beta coefficient 0.0367) and ER- breast tumors (6.5 × 10−7, beta coefficient 0.1798)." (PMID 33019728, 2020). "In conclusion, we define a positive relationship between leptin, LepR and FGFR1 in primary human breast tumors and a positive relationship between LepR and FGFR1 in the tissue adjacent to tumors." (PMID 33019728, 2020). "Fibroblast growth factor receptor 1 (FGFR1) has been linked to the progression, proliferation, migration and survival of breast tumor cells." (PMID 33316872, 2020). "FGFR1 amplification and overexpression have been frequently observed in ER+ breast tumors exhibiting an increased proliferation rate and reduced distant metastasis-free survival." (PMID 33081025, 2020). "In this vein, treatment with AZD4547 has shown a higher antitumor activity in FGFR2-amplified gastroesophageal cancers with respect to FGFR1-amplified breast tumors (NCT01795768)." (PMID 33081025, 2020). "Next, we compared the relationship between leptin mRNA and FGFR1 mRNA among primary breast tumors divided into subgroups according to FGFR1 copy-number level per gene expression by the Genomic Identification of Significant Targets in Cancer (GISTIC)." (PMID 33019728, 2020). "Our bioinformatics results analyze publicly available genomic data to describe the expression of FGFR1 and leptin in breast tumors." (PMID 33019728, 2020). "Human breast tumors with FGFR1 overexpression possess higher cell proliferation rates and have poor prognosis." (PMID 30111373, 2018). "To investigate the role of TNFAIP3 in FGFR1-promoted breast tumor growth in vivo, we injected DCIS-iFGFR1 #2 parent control cells and TNFAIP3 KO DCIS-iFGFR1 cells into the fat pads of nude mouse mammary glands." (PMID 30111373, 2018). "In breast tumours the 8p11-12 amplicon is broad resulting in increased copy number of FGFR1 and of multiple neighboring genes and studies have shown that some of these neighboring genes, for example WHSC1L1, BAG4 and DDHD2, can be oncogenic." (PMID 26905262, 2016).
breast tumors (continued). "FGFR1 amplification was analysed in tissue microarrays comprising a cohort of 880 unselected breast tumours by means of chromogenic in situ hybridisation using inhouse-generated FGFR1-specific probes." (PMID 17397528, 2007). "Analysis of patient ER + breast tumor transcriptomes from the TCGA and METABRIC datasets demonstrated a strong positive association between expression of FGF2 and stemness signatures, which was further enhanced in tumors with high FGFR1 expression." (PMID 38553760, 2024). "Human breast tumors with FGFR1 overexpression also exhibited a poor prognosis." (PMID 36778115, 2023). "Herein, we demonstrate a relationship between FGFR1, leptin, and LepR in human breast tumors." (PMID 33019728, 2020). "While the studies herein do not fully elucidate these complexities, they provide relationship data on two receptors in breast tumors that may be influenced by excess adipose tissue and drive tumor progression, LepR and FGFR1." (PMID 33019728, 2020). "However, the low number of FGFR1 deep deletion breast tumors available for analysis (n = 4) should be noted." (PMID 33019728, 2020). "Herein, we found that, of all primary tumors in 29 different tissues, primary breast tumors demonstrated the most significant relationship between leptin mRNA and FGFR1 mRNA and had the highest levels of average leptin mRNA among other primary cancers of comparison." (PMID 33019728, 2020). "Interestingly, significantly higher leptin levels were observed in FGFR1 amplification, gain, and diploid ER- tumors compared with these copy number states in ER+ breast tumors (p < 0.05)." (PMID 33019728, 2020). "Three-quarters of triple-negative BCs harbour at least one amplicon, however, their recurrence rates are lower than those of high-level CNAs found in ER-positive/ HER2-negative and HER2-positive BC subtypes (e.g. ERBB2-amplicon in HER2, and CCND1 and FGFR1 in luminal breast tumours)." (PMID 23151021, 2012). "To examine whether FOXQ1 upregulation is required for FGFR1 signaling-promoted breast tumor growth in vivo, we injected control DCIS-iFGFR1 cells with sh-NC expression and FOXQ1-knockdown DCIS-iFGFR1 cells with sh-FOXQ1-1/2 expression into the mammary gland fat pads of female BALB/c-nu mice." (PMID 36778115, 2023). "Therefore, a high FGFR1/leptin/FGFR1 breast tumor signature may be most detrimental when circulating levels of FGFs and leptin are elevated." (PMID 33019728, 2020). "Our results demonstrated that FGFR1/2/3 genomic alterations, primarily FGFR1 amplification, were present in approximately 20% of HR + HER2− breast tumors, 23.8% of HER2+ breast tumors, and 24% of TNBC." (PMID 38895905, 2024). "The CNA profile of the primary breast tumour, the bone metastasis and the PDX, were highly similar with focal amplification of FGFR1, FGFR2 and CCND1 and CN gains of CCNE2." (PMID 32792481, 2020). "Patient’s breast tumour and bone metastasis-derived PDX show amplification of FGFR1, MYC, CCNE2, CCND1 and AURKA." (PMID 32792481, 2020). "Further corroborating these findings, in the present study a positive correlation between FGFR1 and CTGF expression was assessed by a bioinformatic analysis on 1904 breast tumor samples retrieved from METABRIC dataset." (PMID 30866584, 2019). "Indeed, some breast tumors with copy number changes in both ERBB2 and FGFR1 were recently described." (PMID 23343422, 2013). "The results also suggest that the expression of FGFR1 itself is regulated by FGF-8 and FGF signaling, which may be of importance in breast tumors expressing FGFs at a high level." (PMID 23185502, 2012).